BRAF (B-Raf proto-oncogene, serine/threonine kinase)
Diseases named in the same sentence as BRAF in open-access papers (continued):
Sharing a sentence is not in itself a finding about the gene and the disease.
papillary thyroid carcinoma (continued). "Phase II clinical trials showed that vemurafenib represented a potential new treatment option for BRAF‐V600E‐positive papillary thyroid cancer and NSCLC with BRAF V600 mutations." (PMID 36254250, 2022). "TERT promoter mutation has recently emerged as a promising prognostic biomarker for aggressive papillary thyroid cancer (PTC), along with BRAF B600E mutation." (PMID 36230856, 2022). "Papillary thyroid carcinoma (PTC) is one of most prevalent malignant endocrine neoplasms, and it is associated with a high frequency of BRAF gene mutations, which lead to lymphatic metastasis and distant metastasis that promote tumor progression." (PMID 35123502, 2022). "Papillary thyroid carcinoma cases showed strong positive cytoplasmic stain of BRAF V600E immunohistochemistry, score index 12, and quick H score 300 with magnification power 10, 40, in (A) and (B), respectively." (PMID 35646190, 2022). "BRAF mutation is a representative oncogenic mutation, with a frequency of 60% in papillary thyroid carcinoma (PTC), but the reasons for the poor prognosis and more aggressive course of BRAF-mutated PTC are controversial." (PMID 35757399, 2022). "As for the PTC patients, studies on BRAF inhibitors have mainly focused on radioactive iodine refractory differentiated thyroid cancer, and relevant clinical trials are in progress (NCT02145143; NCT04462471; NCT04940052; NCT01947023; NCT04554680; NCT05182931)." (PMID 35910024, 2022). "In this pathway, BRAF-mutations and RET/PTC rearrangements can promote the transformation of thyroid follicular cells into papillary thyroid cancer, which is considered as a hallmark for PTC development and progression." (PMID 34221185, 2021). "We found that five of the nine cases of BRAF V600E-positive papillary carcinoma were in the 20-30-year age group." (PMID 34345541, 2021). "In the BRAF-positive papillary carcinomas, five cases were aged 20-30 years, eight were female, eight (88.88%) were euthyroid, and one was hypothyroid." (PMID 34345541, 2021). "In our cohort, 31% of cases of papillary thyroid carcinoma (PTC) and 18.72% of follicular neoplasms expressed the BRAF V600E mutation." (PMID 34345541, 2021). "It was found up‐regulated WIPF1 played a key role in BRAF V600E‐promoted papillary thyroid cancer aggressiveness." (PMID 34245091, 2021). "Another study has revealed association between the presence of BRAF V600E mutation and with lower levels of BANCR in papillary thyroid carcinoma." (PMID 34409032, 2021). "Combined statistical validation of HBME-1, galectin-3, and BRAF V600E co-expression in differentiating among papillary thyroid carcinoma, papillary thyroid hyperplasia, follicular adenoma, and follicular carcinoma." (PMID 34934597, 2021). "Given the predominance of BRAF mutations in RAI-R DTC, it is possible that classic papillary thyroid cancer and tall-cell variant more often develop to refractory disease." (PMID 34630336, 2021). "The nine cases of BRAF-positive papillary carcinomas predominantly comprised individuals aged 20-30 years, were almost all female (8/9), and were euthyroid (8/9, 88.88%)." (PMID 34345541, 2021). "Scoring for nuclear and other microscopic features revealed characteristic features compared with other features observed for BRAF-positive papillary carcinomas." (PMID 34345541, 2021). "Molecular signatures such as BRAF V600E and TERT have been shown to be associated with aggressive variants and advanced stage of papillary thyroid carcinoma." (PMID 33910629, 2021).
papillary thyroid carcinoma (continued). "The molecular assay by dPCR was first established to specifically and accurately detect and quantify wild-type BRAF and variant BRAF in DNA from human follicular thyroid carcinoma–derived FTC-133 and papillary thyroid carcinoma–derived BCPAP cells." (PMID 34613404, 2021). "BRAF (V600E) was chosen for this pilot study as it is the most common genetic alteration noted in PTCs, which is also the most common type of well-differentiated thyroid cancer." (PMID 34475951, 2021). "The level of B-Raf proto-oncogene (BRAF)-activated lncRNA (BANCR) was found to be higher in papillary thyroid carcinoma than in counterpart tissue and was involved in cell proliferation and autophagic activation." (PMID 33233671, 2020). "In parallel, positron-emission tomography had revealed a marked uptake in the right thyroid lobe, a thyroid lobectomy was then performed, and the pathology showed a BRAF-positive papillary thyroid carcinoma." (PMID 32571242, 2020). "Clinical-pathological characteristics according to the status of BRAF, RAS, and TERT mutations and RET rearrangements in papillary thyroid carcinomas." (PMID 32425887, 2020). "This study was conducted to evaluate COX-2 expression in a large cohort of Middle Eastern papillary thyroid carcinoma (PTC), and further evaluate the prognostic significance of COX-2 expression in strata of BRAF mutation status." (PMID 33327467, 2020). "miR-9 has an inhibitory role in papillary thyroid cancer by targeting BRAF and reduces metastatic behavior in triple-negative breast cancer by targeting NOTCH1." (PMID 32258122, 2020). "In the present study we tried to focus on a cohort of patients with early serological persistent disease of classic papillary thyroid cancer, evaluated by F18-FDG PET/CT and BRAF mutation." (PMID 32575591, 2020). "In papillary thyroid carcinoma, 60% of cases show activating somatic alterations of genes encoding effectors in the MAPK signaling pathway, including BRAF and RAS." (PMID 31426419, 2019). "As expected, the BRAF V600E mutation and RET-PTC1 translocation were detected in the samples of papillary carcinoma only, whereas the PAX8-PPARγ translocation was found only in follicular carcinomas." (PMID 31660895, 2019). "In our study, we tested the effect of BRAF V600E inhibitor PLX4032 or in combination of the MEK/ERK inhibitor PD98059 on RAI uptake and NIS expression, in papillary thyroid cancer cell (PTC) with mutated BRAF600E." (PMID 30337961, 2018). "BRAF is a serine/threonine kinase that regulates cell proliferation through MEK/ERK signaling pathway and is the most common mutation in papillary thyroid cancer." (PMID 28430585, 2017). "Herein, we showed that lapatinib prevented MAPK rebound and sensitized BRAFV600E-positive papillary thyroid cancer cells to BRAF/MEK inhibitors." (PMID 28423638, 2017). "Mutations of BRAF (B-type Raf kinase) were detected in 23 and mutation of NRAS (Neuroblastoma RAS Viral Oncogene Homolog) in 2 papillary thyroid cancers." (PMID 28493027, 2017). "For example, in the Hürthle cell variant of papillary thyroid carcinomas, there is a high prevalence of RET-PTC rearrangements and BRAF mutations." (PMID 29100371, 2017). "RET/PTC rearrangement, BRAF, NRAS, and KRAS mutations are considered to be mutually exclusive in papillary thyroid carcinoma." (PMID 28493027, 2017). "Mutations of BRAF, KRAS, and NRAS were tested in tissue samples of 53 patients (39 papillary thyroid cancers, 10 with follicular variant; 3 follicular thyroid cancers, 1 oxyphilic variant)." (PMID 28493027, 2017). "Redifferentiation therapy with BRAF/MEK inhibitors to facilitate treatment with radioiodine represents a good choice for radioiodine-refractory differentiated thyroid carcinoma, but recent initial clinical outcomes were modest." (PMID 28423638, 2017). "The BRAF V600E and telomerase reverse transcriptase (TERT) promoter mutations have been reported in papillary thyroid carcinoma (PTC)." (PMID 27064992, 2016).
papillary thyroid carcinoma (continued). "Clinicopathological characteristics of classic papillary thyroid carcinoma patients with BRAFV600E or wild-type BRAF." (PMID 27410688, 2016). "The majority of mice with high expression of BRAF protein developed papillary thyroid cancer, while in lines with less abundant protein, PTC cases were less frequent." (PMID 26625260, 2015). "The tg2 line was characterized by the highest level of the BRAFV600E protein and the highest frequency of papillary thyroid carcinomas with the 76% of cases (19 out of 25 BRAF(+) mice)." (PMID 26625260, 2015). "Dedicated passes are also needed for studies to detect genetic alterations such as BRAF mutation or RET/PTC chromosomal rearrangements, which are very promising for the diagnosis of papillary carcinoma." (PMID 25688327, 2015). "Normal BRAF-wild-type thyroid cells and BRAFV600E-mutated papillary thyroid cancer cells were subjected to proliferation assays and analyzed for cell death by immunofluorescence." (PMID 24673746, 2014). "Nthy-ori 3–1 are normal transformed thyroid cells with wild-type BRAF and BCPAP are papillary thyroid cancer cells harboring the BRAFV600E mutation." (PMID 24673746, 2014). "BRAF and RAS mutations and RET/PTC gene rearrangements were found in 65.1%, 0%, and 1.6% of papillary carcinomas, respectively." (PMID 24591770, 2014). "We analyzed mutation status of BRAF and RAS (HRAS, NRAS, and KRAS) oncogenes in 34 papillary thyroid cancer samples using MALDI-TOF-MS." (PMID 24367375, 2013). "RET/PTC (Rearranged in Transformation/Papillary Thyroid Carcinoma) re-arrangement, BRAF (V-Raf murine sarcoma viral oncogene homolog B) and RAS (Rat Sarcoma viral oncogene homolog) point mutations are frequently observed in papillary thyroid cancer." (PMID 24367375, 2013). "We used BRAF-induced papillary thyroid cancer (PTC) mouse models to examine the role of TAMs in PTC progression." (PMID 23372702, 2013). "Although the most common is RET/PTC, BRAF/AKAP9 is also found predominantly in radiation-induced papillary thyroid carcinoma." (PMID 23165002, 2013). "In papillary thyroid carcinoma, genetic alterations such as RET/TRK rearrangements or BRAF and RAS mutations usually lead to signaling derangements in the mitogen-activated protein kinase pathway." (PMID 23165002, 2013). "The experiments included in the present study indicated a specificity of almost 100% and a high predominance of the BRAF mutation in PTC, distinguishing the marker in the planning and medical management of papillary carcinoma of the thyroid." (PMID 23946802, 2013). "In previous studies of papillary thyroid cancer, although methylation of RASSF1A and BRAF mutation were detected in a mutually exclusive manner, methylation of RAR-β2 or MLH1 significantly correlated to BRAF mutation." (PMID 24367375, 2013). "The frequency of RET/PTC rearrangements and BRAF mutations observed was in accordance with previous reports, thus showing that RET/PTC is the most common genetic alteration in papillary carcinomas from young patients." (PMID 22481925, 2012). "BRAF belongs to the RAF family of serine/threonine kinases and the V600E mutation results in constitutive activation in 45% of papillary thyroid carcinomas in adults." (PMID 22654559, 2011). "The combined detection of galectin-3 and BRAF V600E improves the diagnosis in FNAB with cytological findings that give rise to suspicions of papillary thyroid carcinoma; and this detection finds clinical application in selected cases." (PMID 22654559, 2011). "The incidence of NTRK1 translocations is exclusive to papillary thyroid cancer, but with a much lower frequency (5–15%) than RET translocations or BRAF point mutations." (PMID 24281099, 2010). "As a biomarker, BRAF is almost exclusively found in papillary thyroid carcinomas, and can be used as a marker for this tumor type." (PMID 24281099, 2010).
papillary thyroid carcinoma (continued). "Another activating BRAF mutation, BRAFK601E, has been found in thyroid adenomas and the follicular variant of papillary thyroid cancer." (PMID 24281099, 2010). "Four genetic defects, at the somatic level, are associated with papillary cancers of the thyroid: chromosomal recombination events affecting RET and TRKA, and activating mutations of RAS and BRAF." (PMID 17667921, 2007). "Recently, BRAF rearrangements have been reported in papillary carcinoma and shown to be specific to this tumor." (PMID 16603062, 2006). "BRAF exon-skipping events were identified in treatment-naïve papillary thyroid carcinomas." (PMID 41492106, 2026). "The BRAF gene plays an essential role in papillary thyroid carcinoma (PTC)." (PMID 41199838, 2025). "Unlike BRAF p.V600E-mutated tumors, which are typically conventional papillary carcinomas, tumors with non-V600E BRAF mutations tend to have a follicular pattern and are often histologically classified as follicular adenoma or carcinoma, I-EFVPTC, or NIFTP." (PMID 41175860, 2025). "NTRK-rearranged tumors resemble BRAF V600E-like conventional papillary carcinomas." (PMID 41175860, 2025). "In papillary thyroid cancer, a BRAF mutation occurs in 36–83% of cases and, although of some debate, by itself BRAF mutation does not likely confer an adverse prognosis." (PMID 40869231, 2025). "BRAF p.V600E is also detected in aggressive, high-grade tumors arising from the progression of conventional papillary carcinoma, with reported frequencies ranging from 10 to 50–60% for high-grade non-anaplastic carcinomas (HGDTC and PDTC) and from 10 to 50% for anaplastic carcinomas." (PMID 41175860, 2025). "However, this possibility is refuted by the treatment response of both pleural metastasis of papillary thyroid carcinoma and lung tumours of NSCLC to dabrafenib and trametinib combination therapy targeting BRAF V600E mutated tumour." (PMID 39950095, 2025). "Cervical lymph node status is critical when planning surgery for papillary thyroid carcinoma, yet most tools treat the BRAF V600E mutation as a simple yes/no finding." (PMID 41228353, 2025). "In particular, our data strongly support that the PDTC subtype—as defined by Turin consensus criteria—is separate even molecularly from the other high-grade differentiated thyroid cancers, mainly because of the high prevalence of NRAS mutations and the extremely low prevalence of BRAF mutations." (PMID 41123735, 2025). "Our analysis of histological types revealed a significant predominance of papillary carcinoma in patients with the BRAF mutation compared to those without this mutation." (PMID 39767732, 2024). "Several studies have suggested that papillary carcinoma is more common in patients with the BRAF mutation compared to those without it." (PMID 39767732, 2024). "Meanwhile, it was also revealed that for newly diagnosed well-differentiated thyroid carcinoma, BRAF does not independently predict the risk of cancer-related mortality." (PMID 39363900, 2024). "Furthermore, the BRAF V600E-specific inhibitor dabrafenib can distinguish BRAF V600E from non-BRAF V600E papillary thyroid carcinomas." (PMID 37760447, 2023). "In addition, we analyzed the impact of the BRAF V600E-specific inhibitor dabrafenib, as well as the generic RAF inhibitors sorafenib and regorafenib, in a subgroup of BRAF V600E and non-BRAF V600E papillary thyroid carcinomas." (PMID 37760447, 2023). "In line with independent studies reporting the association of metabolic gene signatures and clinicopathological features in papillary thyroid carcinomas, our work provides evidence of a strong perturbation of metabolic genes between the two distinct tumour subtypes (i.e., BRAF- and RAS-like PTCs)." (PMID 37198319, 2023).
papillary thyroid carcinoma (continued). "Based on this data, it is not routinely recommended in the clinic to test for BRAF status for the initial presentation of differentiated thyroid cancer (DTC) such as PTC, particularly in low-risk patients who do not present with worrisome features." (PMID 38115146, 2023). "In the BRAF group all tumors were papillary thyroid cancers (PTC)." (PMID 35246262, 2022). "The application of molecular markers (e.g., the application of BRAF growth promoter in thyroid papillary carcinoma) and IHC (e.g., the application of CD-10 in RCC) may be further helpful in the diagnosis of FNAB." (PMID 35740683, 2022). "Moreover, the results of the LDH assay further showed that STS promoted cellular death of papillary thyroid cancer cells, and the death level of papillary thyroid cancer cells knocked down by BRAF V600E was further aggravated by STS treatment." (PMID 35748101, 2022). "BRAF-positive papillary thyroid carcinoma stage at presentation." (PMID 34345541, 2021). "In particular, the BRAF V600E point mutation is the most frequent alteration in papillary thyroid cancers (PTC) (45–60%); RAS and then TERT promoter point mutations can be also found and gene fusions (TRK 1/3, RET, ALK, BRAF) are detectable in only 15% of tumor samples." (PMID 34638232, 2021). "In a series of 200 resected conventional papillary carcinomas from South Korea, Seo et al29 showed that 93% of the surgical specimens were positive for BRAF p.V600E and that 96% of these cases could be detected in the corresponding malignant FNAB." (PMID 33052631, 2021). "BRAF-positive papillary thyroid carcinoma and hormonal status." (PMID 34345541, 2021). "Number of BRAF-positive papillary thyroid carcinoma and age distribution." (PMID 34345541, 2021). "BRAF gene is used to assist in the diagnosis of benign and malignant thyroid nodules, which greatly reduces the misdiagnosis rate in clinical diagnosis and improves the accuracy of preoperative diagnosis of patients with papillary thyroid cancer." (PMID 34497810, 2021). "BRAF gene is used for clinical diagnosis of papillary thyroid cancer." (PMID 34497810, 2021). "Papillary carcinoma of the thyroid is characterized by a high prevalence of RET chromosomal rearrangements, and of point mutations of RAS or BRAF proto-oncogenes, all of which are able to trigger the activation of mitogen-activated protein kinase (MAPK) cascade, as well as NTRK fusions." (PMID 33277509, 2020). "Papillary carcinoma, in particular, is mostly related to mutations that activate the MAPK signalling pathway, including RET/PTC rearrangements and point mutations of the BRAF and RAS genes." (PMID 32722293, 2020). "BRAF mutations are the predominant genetic changes in papillary thyroid carcinoma but the incidence of BRAF mutation in HCC is not common." (PMID 33374707, 2020). "Analysis of the BRAF V600E mutation in patients with differentiated thyroid neoplasia is not undertaken routinely, because differentiated thyroid cancer (DTC), especially the papillary form, has a high rate of response to treatment." (PMID 32575591, 2020). "Similarly, CXCR4 levels correlate both with the degree of tumor aggressiveness and with BRAF status in papillary thyroid carcinomas." (PMID 31762942, 2019). "In addition, a previous study demonstrated that expression of exogenous miR-9-5p decreased BRAF protein and mRNA levels, and BRAF is a direct target of miR-9-5p in the tumorigenesis of papillary thyroid cancer (PTC)." (PMID 30965609, 2019). "Additionally, it has been suggested that if any additional factors, such as extrathyroidal invasion, lymph node metastases, or the BRAF V600E mutation, are found, PTMC should be treated as a “larger” papillary thyroid cancer." (PMID 30305094, 2018). "PTC, papillary thyroid carcinoma; BRAFWT, BRAF wild type; BRAFV600E, positive for BRAF mutation." (PMID 30454026, 2018).